GPR137B (G protein-coupled receptor 137B)
Description:
Lysosomal integral membrane protein that regulates the localization and activity of mTORC1, a signaling complex promoting cell growth in response to growth factors, energy levels, and amino acids. Interacts with Rag GTPases and increases the lysosomal localization and activity of Rag GTPases and thereby regulates mTORC1 translocation and activity in lysosome. Involved in the regulation of lysosomal morphology and autophagy. Also acts as a negative regulator of osteoclast activity (By similarity). Involved in interleukin-4-induced M2 macrophage polarization (By similarity).
Synonyms: TM7SF1
Tractability: Antibody: its Gene Ontology location is reachable by antibodies, with high confidence; UniProt predicts a signal peptide or a membrane-spanning region.
Gene: Protein-coding gene on chromosome 1 (236,142,148 to 236,221,865, forward strand). Ensembl gene ENSG00000077585.
Subcellular location: Lysosome membrane
Gene Ontology:
Molecular function: protein binding
Biological process: positive regulation of protein localization to lysosome; positive regulation of TORC1 signaling; regulation of autophagy; regulation of GTPase activity; negative regulation of bone resorption; negative regulation of osteoclast differentiation; regulation of macrophage activation
Cellular component: lysosomal membrane; membrane; plasma membrane
Genetic constraint (gnomAD): Loss-of-function variants: 22 observed, 22.78 expected, observed/expected ratio (o/e) 0.97, 90% interval 0.69 to 1.38. The upper end of that interval is the gene's LOEUF score, 1.38, which puts it in group 5 of 6, group 1 being the genes least tolerant of losing a copy. Missense variants: 336 observed, 339.29 expected, observed/expected ratio (o/e) 0.99, 90% interval 0.9 to 1.08. Synonymous variants: 171 observed, 153.52 expected, observed/expected ratio (o/e) 1.11, 90% interval 0.98 to 1.26.
Homologues: Orthologues: chimpanzee GPR137B (100% identical), macaque GPR137B (96% identical), pig GPR137B (95% identical), dog GPR137B (94% identical), rabbit GPR137B (92% identical), mouse Gpr137b (91% identical), rat Gpr137b (91% identical), guinea pig GPR137B (89% identical), tropical clawed frog gpr137b (74% identical), zebrafish gpr137ba (67% identical), zebrafish gpr137bb (61% identical). Paralogues in human: GPR137 (48% identical), GPR137C (44% identical).
Diseases named in the same sentence as GPR137B in open-access papers:
GPR137B is named in the same sentence as 7 diseases in open-access papers, as found by Europe PMC text mining. Sharing a sentence is not in itself a finding about the gene and the disease. The quoted sentences say what the papers report.
infertile (1 paper, 2017). "DMRTB1 was a down-regulated common gene among MArrest, oligospermia and Ikbkap KO, GPR137B was common among teratospermia, Bcl6b and Pou3f1 KD, and LMNB2 was common among Bcl6b, Etv5 and Pou3f1 KD infertile mice." (PMID 29150651, 2017).
pancreatic cancer (1 paper, 2019). "GPR137B upregulation is linked to aggressive forms of pancreatic cancer and associated with increased proliferation in various cancer types but has not been identified as a PCa biomarker yet." (PMID 31640781, 2019).
rheumatoid arthritis (1 paper, 2023). A chronic, systemic autoimmune disorder characterized by inflammation in the synovial membranes and articular surfaces. "In a genome-wide association study, GPR137B was reported to be correlated with hereditary susceptibility for rheumatoid arthritis." (PMID 36836601, 2023).
cancer (2 papers, 2011 to 2019). A tumor composed of atypical neoplastic, often pleomorphic cells that invade other tissues. "Among them, Cd34, protein tyrosine phosphatase, receptor type, F (Ptprf), Txnrd1, Pgd, Ugt1a1, Gpr137b, and dynein light chain Tctex-type 1 (Dynlt1) were connected in a molecular network of cancer-cell cycle-cell death." (PMID 22039513, 2011).
GPR137B also shares sentences with these, for which no sentence is quoted: oligospermia (1 paper); teratospermia (1); tumor (1).